FMR1 (fragile X messenger ribonucleoprotein 1)
Diseases named in the same sentence as FMR1 in open-access papers (continued):
Sharing a sentence is not in itself a finding about the gene and the disease.
atherosclerosis (2 papers, 2022). A disease characterized by the build-up of fatty material and calcium deposition in the arterial wall resulting in partial or complete occlusion of the arterial lumen. "To approach the role of macrophage FMRP in atherosclerosis, we generated a myeloid Fmr1‐deficient mouse model (myFmr1−/−) and induced hyperlipidemia." (PMID 35191199, 2022). "Moreover, systemwide and myeloid‐specific Fmr1 knock‐out mice were protected from hypercholesterolemia‐induced atherosclerosis progression." (PMID 35191199, 2022).
autoimmune disease (2 papers, 2014 to 2021). A disorder resulting from loss of function or tissue destruction of an organ or multiple organs, arising from humoral or cellular immune responses of the individual to their own tissue constituents. "FMR1 is decreased in the thymus of myasthenia gravis (MG) patients, a prototypical autoimmune disease." (PMID 34789272, 2021).
Channelopathies (2 papers, 2015 to 2025). "Although this study focuses on differences in HCN channel activity, it is likely that other channelopathies are present in MD neurons of Fmr1 KO animals." (PMID 39975001, 2025).
colon cancer (2 papers, 2022 to 2023). "The results suggested that the RNA interference scheme targeting FMR1 has great potential in the treatment of colon cancer." (PMID 36347844, 2022).
congenital hypogonadotropic hypogonadism (2 papers, 2021 to 2022). Congenital hypogonadotropic hypogonadism (CHH) is a rare disorder of sexual maturation characterized by gonadotropin (Gn) deficiency with low sex steroid levels associated with low levels of follicle stimulating hormone (FSH) and luteinizing hormone (LH). "Specifically, in 2017, Stuppia and Gatta recommended karyotyping and only FMR1 assessment, while in 2019, Toth and colleagues recommended karyotyping, FMR1 and CYP21A2 testing, as well as congenital hypogonadotropic hypogonadism gene panel testing." (PMID 35451369, 2022).
COVID-19 (2 papers, 2022 to 2023). A disease caused by infection with severe acute respiratory syndrome coronavirus 2. "Similarly, the specific role of VIRMA, ELAVL1, and FMR1 in COVID-19 was mentioned in several studies." (PMID 35655464, 2022). "We observed that RBM15B, HNRNPA2B1, and VIRMA may be protective factors in the development of COVID-19, and the opposite performance was found in ELAVL1, RBM15, FMR1, IGFBP3, and METTL3." (PMID 35655464, 2022).
dementia (2 papers, 2014 to 2021). Loss of intellectual abilities interfering with an individual's social and occupational functions. "This study highlights the challenge for clinicians to diagnose FMR1-premutation carriers, and stresses the importance of genetic screening for CGG repeats within FMR1 for suspected dementia with behavioural features." (PMID 33709078, 2021). "Here, we report two cases with dementia and psychiatric symptoms who were diagnosed as FMR1-premutation carriers either post-mortem or in advanced disease state." (PMID 33709078, 2021).
developmental disabilities (2 papers, 2019 to 2024). "Inclusion of FXS on the Early Check panel will not only provide a mechanism to identify and test theories about outcomes for individuals with FMR1 expansions, but will serve as a prototype for expanded NBS for many conditions resulting in intellectual or developmental disabilities." (PMID 30609779, 2019).
folate deficiency (2 papers, 2018). A nutritional condition produced by a deficiency of FOLIC ACID in the diet. "FMR1 alleles with more than 200 CGG repeats bear chromosomal fragility when cells experience folate deficiency." (PMID 29760651, 2018).
Gait ataxia (2 papers, 2017 to 2025). A type of ataxia characterized by the impairment of the ability to coordinate the movements required for normal walking. "The necessary findings to confirm an FXTAS diagnosis are an FMR1 PM associated with an MRI showing white matter lesions in the middle cerebellar peduncles and/or brain stem (the major neuroradiologic sign) and intention tremor or gait ataxia (the two major clinical signs)." (PMID 28420439, 2017).
gastric cancer (2 papers, 2021 to 2026). A primary or metastatic malignant neoplasm involving the stomach. "In gastric cancer, m6A modifications are mediated by the CNV deletions of ELAVL1, YTHDF2 and FMR1, which then affects tumor formation." (PMID 33926554, 2021).
hemophilia B (2 papers, 2018 to 2022). Hemophilia B is a form of hemophilia characterized by spontaneous or prolonged hemorrhages due to factor IX deficiency. "Our patient was diagnosed with mild hemophilia B after finding an 11 Mb deletion of Xq26.3q28 that included the following genes among others IDS,SOX3,FMR1,AFF2, and F9." (PMID 30264515, 2018).
Hypergonadotropic hypogonadism (2 papers, 2014 to 2022). Reduced function of the gonads (testes in males or ovaries in females) associated with excess pituitary gonadotropin secretion and resulting in delayed sexual development and growth delay. "Fragile X-associated primary ovarian insufficiency (FXPOI) is characterized by oligo/amenorrhea and hypergonadotropic hypogonadism and is caused by the expansion of the CGG repeat in the 5′UTR of Fragile X Mental Retardation 1 (FMR1)." (PMID 35328005, 2022).
Intention tremor (2 papers, 2017 to 2024). A type of kinetic tremor that occurs during target directed movement is called intention tremor. "In 2012, Hall and colleagues reported for the first time a case series of three patients (one man and two women) with intention tremor and other signs typical of FXTAS that were carriers of gray zone FMR1 allele." (PMID 37906407, 2024).
leukoencephalopathies (2 papers, 2023). "CGG trinucleotide repeat expansions outside of the FMR1 loci have recently emerged as a cause of multiple degenerative and developmental disorders, with clinical phenotypes ranging from distal myopathy to motor neuron disease to leukoencephalopathy." (PMID 37352983, 2023). "Recent long‐read sequencing technology has solved these problems, as evidenced by the discovery of noncoding CGG repeat expansions of NOTCH2NLC, FMR1, and NUTM2B‐AS1 in three leukoencephalopathies patients based on long‐read sequencing technology." (PMID 37237429, 2023). "In this study, we investigated dynamic mutations in Chinese patients with adult leukoencephalopathies and discovered that 8.5% of patients had NOTCH2NLC GGC repeat expansions, but none had FMR1 and NUTM2B‐AS1 repeat expansions." (PMID 37237429, 2023).
metastatic tumor (2 papers, 2015 to 2017). "In our protein analyses, fragile X mental retardation protein 1, encoded by the related FMR1 gene on chromosome X, was detected uniquely in three metastatic tumors but was not altered in abundance." (PMID 26305875, 2015).
Onset (2 papers, 2016 to 2022). The age group in which disease manifestations appear. "FXTAS is a late-adult-onset neurodegenerative disorder caused by a premutation (PM) allele (CGG expansion of 55–200 repeats), resulting in FMR1 gene hyperexpression." (PMID 36110216, 2022). "No targeted treatment has yet been proven effective for FXTAS, a progressive adult-onset neurodegenerative disorder affecting many older FMR1 premutation carriers." (PMID 26898832, 2016).
pancreatic cancer (2 papers, 2021 to 2022). "Using RT-qPCR, the three most substantially elevated mRNAs in pancreatic cancer cells in response to co-culture with MSCs were Notch1, FMR1, and U2AF2." (PMID 34631547, 2021).
periodontitis (2 papers, 2021 to 2022). An acute or chronic inflammatory process that affects the tissues that surround and support the teeth. "For instance, monocyte abundance is positively correlated with ALKBH5 and negatively correlated with FMR1, indicating increased monocytes infiltrated in periodontitis which is closely affected by the expression of ALKBH5 and FMR1." (PMID 33724691, 2021).
progressive neurodegenerative disorder (2 papers, 2014 to 2018). "FXTAS is a human, progressive neurodegenerative disorder in which the abnormal CGG expansion within the 5′UTR of the FMR1 gene is thought to be the source of abnormal cell function." (PMID 24821701, 2014). "The fragile X–associated tremor/ataxia syndrome (FXTAS) is an adult-onset, progressive neurodegenerative disorder that affects individuals with a premutation (between 55 and 200 CGG repeats) in the fragile X mental retardation 1 (FMR1) gene." (PMID 30158953, 2018).
prostate carcinoma (2 papers, 2020 to 2022). A carcinoma that arises from epithelial cells of the prostate gland. "Seven m6A methylation-related genes (ALKBH5, FMR1, IGFBP3, RBM15B, YTHDF1, YTHDF2, and ZC3H13) were identified as cross-talk genes between prostate cancer and PD." (PMID 36133437, 2022).
rheumatoid arthritis (2 papers, 2013 to 2022). A chronic, systemic autoimmune disorder characterized by inflammation in the synovial membranes and articular surfaces. "Here we show that treatment with methotrexate (MTX), an agent used for the long-term treatment of patients with rheumatoid arthritis and found to decrease cellular methylation including DNA methylation, also results in FMR1 expression but no detectable FMRP levels." (PMID 24020679, 2013).
social anxiety disorder (2 papers, 2016 to 2024). "Individuals with FXS are often diagnosed with social phobia and social interaction deficits and some of these behaviors have been recapitulated in the Fmr1 KO mouse model, although findings from the different studies are variable." (PMID 39308631, 2024).
Type 2 Diabetes (2 papers, 2021 to 2025). "Fmr1 KO mice appear to have high insulin sensitivity, as well as lower amounts of blood glucose and fat, which is surprising given that some phenotypes are rescued by metformin, the first-line drug to treat Type 2 Diabetes because of its ability to decrease blood glucose." (PMID 41037592, 2025). "Specifically, we asked if metformin, a first-line drug to treat type 2 diabetes, which also alleviates some symptoms in FXS as well as phenotypes in Fmr1 KO mice and flies, rescued sleep phenotypes." (PMID 41037592, 2025).
acute myeloid leukemia (1 paper, 2021). Acute myeloid leukemia (AML) is a group of neoplasms arising from precursor cells committed to the myeloid cell-line differentiation. "FMR1 is shown to have regulated histone methylation H4K27m3 in lymphoblastoid and fibroblast cell lines while PRG2 has been discerned to get hypomethylated in acute myeloid leukemia." (PMID 34788504, 2021).
alcoholism (1 paper, 2024). "Evaluation of gene expression in the cocaine addiction, alcoholism, and amphetamine addiction pathways for male and female WT and Fmr1 KO mice revealed that approximately 30% of the DEGs were upregulated and 70% were downregulated in the Fmr1 KO mice." (PMID 39308631, 2024).
amnesia (1 paper, 2015). Pathologic partial or complete loss of the ability to recall past experiences ( AMNESIA, RETROGRADE) or to form new memories ( AMNESIA, ANTEROGRADE). "Effects of CDRI-08 in up regulation of GluN2B subunit of the NMDA glutamate receptor and Fmr-1 gene expression in scopolamine-induced amnesia and cobalt chloride-induced hypoxic mice, respectively have recently been reported by us." (PMID 26161865, 2015).
Atrophy (1 paper, 2018). Any weakening or degeneration, especially through lack of use. "Indeed, it appears that atrophy of the midbrain and pons cross-sectional area may be a common phenotypic characteristic for FMR1 premutation carriers, while reductions in MCP width may be prognostic to FXTAS symptoms and progression." (PMID 29988561, 2018).
basal cell carcinoma (1 paper, 2023). A carcinoma involving the basal cells. "Through OCLR algorithm, it can be seen that mRNAsi, EREG-MRNASI value has significant difference between the two clusters (p < 0.05), suggesting that FMR1, LRPPRC, RBMX, YTHDC2 and IGF2BP1 may affect CRC by regulating the pathway of basal cell carcinoma." (PMID 37194014, 2023).
cervical squamous cell carcinoma (1 paper, 2022). A squamous cell carcinoma arising from the cervical epithelium. "The results showed that the expressions of WTAP were downregulated; and the expressions of four m6A-RMRs such as HNRNPA2B1, IGF2BP2, FMR1, and HNRNPC were upregulated in patients with preinvasive and invasive cervical squamous cell carcinomas compared with normal controls." (PMID 35211628, 2022).
childhood asthma (1 paper, 2021). "Moreover, in another study on childhood asthma found that m6A regulators also played a crucial role, and screened five candidate m6A regulators (FMR1, KIAA1429, WTAP, YTHDC2 and ZC3H13) to predict the risk of childhood asthma." (PMID 34647423, 2021).
chordoma (1 paper, 2013). Chordomas are rare malignant tumors arising from embryonic remnants of the notochord in axial skeleton. "By comparing methylation patterns of blood from healthy individuals and chordoma patients we found 20 significantly differentially methylated genes; 15 hypermethylated in chordoma (for example RASSF1, KL, RARB, HIC1, and FMR1) and 5 hypomethylated (HSD17B4, BAZIA, STAT1, NEUROGL, and JUP)." (PMID 23533570, 2013).
corticobasal syndrome (1 paper, 2018). Corticobasal syndrome (CBS) is a rare neurodegenerative disease characterized by multifaceted motor system dysfunctions and cognitive defects such as asymmetric rigidity, bradykinesia, limb apraxia, and visuospatial dysfunction. "This is, to best of our knowledge, the first report describing a pathologically confirmed progressive supranuclear palsy – corticobasal syndrome (PSP-CBS) variant case in a FMR1 premutation carrier." (PMID 30158953, 2018). "Here, we report histological findings of a patient with a FMR1 premutation, who had a severe dopamine deficiency, according to [123I] ioflupane SPECT, and showed clinical signs compatible to the progressive supranuclear palsy – corticobasal syndrome variant (PSP-CBS) as we have previously reported." (PMID 30158953, 2018).
cyst (1 paper, 2012). A sac-like closed membranous structure that may be empty or contain fluid or amorphous material. "Our data indicate that fmr1 and Capr genetically interact to regulate cyst encapsulation and female fecundity." (PMID 22493746, 2012).
drug dependence (1 paper, 2024). "A recent study showed that Fmr1 mRNA is reduced in leukocytes of patients diagnosed with alcohol or drug dependence in comparison to healthy controls, further demonstrating a potential link between Fmr1 and drug dependence." (PMID 39308631, 2024).
Dyscalculia (1 paper, 2022). A specific learning disability involving mathematics and arithmetic. "In this present study, neuropsychological results excluded impairments in written language and phonological processing in the two children with expanded FMR1 alleles and dyscalculia." (PMID 35719251, 2022). "These numbers seem small, reflecting the complexities underlying a population design necessary to detect FMR1 expansions (due to their low frequency) and dyscalculia (due to the wide range of tests needed to diagnose it)." (PMID 35719251, 2022). "The investigated hypothesis was that dyscalculia is a phenotype associated with expanded FMR1 alleles in demographically recruited school-age children." (PMID 35719251, 2022). "FMR1 expansions in the gray zone may contribute to dyscalculia in otherwise healthy and normally intelligent children." (PMID 35719251, 2022). "Indeed, FMR1 provides one of the larger contributions of a single gene to the dyscalculia phenotype reported so far." (PMID 35719251, 2022). "However, no study has investigated the contribution of FMR1 premutation or gray zone alleles to dyscalculia in population samples of school-age children using a detailed neuropsychological assessment." (PMID 35719251, 2022).
dyslexia (1 paper, 2014). A learning disorder characterized by an impairment in processing written words. "Thus, it is reasonable to speculate that deficits of KIAA0319 and FMR1 might give rise to dysfunction in M pathway for children with dyslexia." (PMID 25071661, 2014).
Dystonia (1 paper, 2016). An abnormally increased muscular tone that causes fixed abnormal postures. "Even though we confirmed the biochemical interaction between HTor1A and FMR1 in human plasma in this study, the possible genetic interaction between these two proteins in humans could be supported by the fact that the age of onset for DTY1 dystonia is in adolescence." (PMID 27313903, 2016).
facioscapulohumeral muscular dystrophy (1 paper, 2023). An autosomal dominant disorder affecting the skeletal muscles of the face, scapula, and upper arm. "For analysis of repeat disorders, Bionano Genomics developed two targeted workflows, EnFocus FSHD, which measures repeat contractions in facioscapulohumeral muscular dystrophy, and EnFocus fragile X analysis, which measures repeat expansion in the FMR1 gene." (PMID 37298158, 2023).
focal dystonia (1 paper, 2025). A dystonia that is localized to a specific part of the body. "ONT data also provided unexpected insights into apparent mosaic expanded repeats in FMR1 in a subject with isolated focal dystonia." (PMID 41028987, 2025).
FRAXE syndrome (1 paper, 2018). "Fragile‐X syndrome (FMR1) and FRAXE syndrome (AFF2) are well‐known causes of X‐linked recessive intellectual disability." (PMID 30264515, 2018).
gout (1 paper, 2022). A condition characterized by painful swelling of the joints, which is caused by deposition of urate crystals. "Therefore, there is reason to believe that the mitochondria dysregulation due to elevated levels of FMR1‐mRNA can lead to inflammasome activation manifesting into gout." (PMID 36447664, 2022).
hyperandrogenism (1 paper, 2013). Excessive secretion of androgens from the adrenal glands or gonads. "Whether the early stages of PCO-like phenotype are associated with hyperandrogenism is unknown but the same sub-genotype of FMR1 was recently also demonstrated to convert DHEA to TT less efficiently than other FMR1 genotypes did." (PMID 23805952, 2013).
Hypercholesterolemia (1 paper, 2022). An increased concentration of cholesterol in the blood. "We found that FMRP S499 phosphorylation, which leads to FMRP‐mediated translational suppression, was 1.4‐fold elevated by a chronic exposure to hypercholesterolemia, whereas FMRP protein and Fmr1 mRNA expression levels remained unchanged." (PMID 35191199, 2022).
hyperlipidemia (1 paper, 2022). "Next, we induced hyperlipidemia in Fmr1−/− and Fmr1+/+ mice using a combination of AAV_PCSK9 injection and feeding with a WD." (PMID 35191199, 2022). "We tested this notion using Fmr1−/− and Fmr1+/+ mice in which hyperlipidemia was induced by combining AAV_PCSK9 injection with a WD." (PMID 35191199, 2022).
Hypertension (1 paper, 2020). The presence of chronic increased pressure in the systemic arterial system. "In both sexes, individuals with FXTAS have higher odds of having hypertension compared with age-matched noncarriers and the risk of having hypertension is related to FMR1 mRNA levels." (PMID 32575683, 2020).
itch (1 paper, 2020). "Taken together, our results implicate that Fmr1 KO mice fail to produce contagious itch behavior, independently from spontaneous scratching, look, and self-grooming behaviors." (PMID 33077777, 2020). "This will further establish the consistency or variance of contagious itch behavior present in WT and Fmr1 KO mice." (PMID 33077777, 2020). "Lastly, to test whether Fmr1 KO mice showed other behavioral changes, we measured self-grooming behaviors during our contagious itch assay." (PMID 33077777, 2020). "Specifically, WT mice watching a scratching demonstrator exhibited an average of approximately 0.54 imitative scratching bouts over 60 min; however, Fmr1 KO mice watching the same scratching demonstrator failed to exhibit any contagious itch behavior over the same period." (PMID 33077777, 2020).